MCM7 (minichromosome maintenance complex component 7)
Diseases named in the same sentence as MCM7 in open-access papers (continued):
Sharing a sentence is not in itself a finding about the gene and the disease.
tumor (continued). "The key genes, CDK2, MCM7, and RUVBL2, have all been observed to have an increased level of expression for adolescent hosts irradiated with protons, which likely contribute to the picture of an overall environment predisposed to both oncogenesis and tumor promotion." (PMID 26253138, 2015). "These miRNAs are members of the miR-106b∼25 cluster located within intron 13 of the Mcm7 gene that has been found to directly target a number of important tumor suppressor pathways and may therefore be involved in the promotion of cellular proliferation in high risk blastemal regions." (PMID 23308219, 2013). "Thus the synergistic effect of miR-106b-93-25 cluster and MCM7 may account for the over-proliferation property of some tumor cells." (PMID 23028803, 2012). "In addition, we clarified the tumor-related arginine methyltransferase PRMT6 could interact with MCM7 in the present study." (PMID 21619671, 2011). "In contrast, tumor promoters such as MYBL2, TYMS, MYC, MCM7, and EGFL7 were downregulated in EF-24–treated cells." (PMID 40986633, 2025). "We next examined the effect of MCM7 inhibition on the proliferation of DKO yBM, BMT, and mouse OS tumor cells." (PMID 38182577, 2024). "Among the MCMs, MCM7 is a major subunit of the putative heteromeric MCM helicase complex and has been reported to be involved in tumor development and progression." (PMID 37696392, 2024). "We biopsied tumor specimens from five patients with PR and PD to detect the protein and mRNA levels of RB1, CDKN2B, PCNA, and MCM7." (PMID 37781033, 2023). "The expression levels of MCM7, CDK6 and POLA1 showed a remarkably elevated trend according to the grade of the tumor, and differences between all grades were statistically significant." (PMID 37005685, 2023). "Especially MCM7 is required for S-phase checkpoint activation upon UV-induced damage, which indicated that the Basal-SCCIS-tumor cells were malignant cells from AK induced by UV damage." (PMID 38099574, 2023). "Seven genes of the prognostic model (COPA, GPX7, ITGB5, MATN3, MCM7, MMP1, and SPP1) have been validated to be related to tumor progression, whereas the remaining three genes, BNDF, GADD45B, and LOX, need to be further analyzed." (PMID 35699863, 2022). "Meanwhile, MCM7 and CDC45, which were involved in this process, were correlated with MCM3 and differentially expressed between normal and tumor tissues." (PMID 36133906, 2022). "In accordance with our above results, Western blot analysis revealed that CCNA2, MCM7 and SKP2 expression were decreased in the MTHFD2 knockdown tumour tissues compared with shCtrl tumour tissues." (PMID 31778025, 2020). "To gain insight into the clinical signature of MCM7 in HCC, we examined the expression levels of MCM7 in 153 paired HCC tumor tissues and adjacent normal liver samples by immunohistochemistry (IHC) staining." (PMID 28182015, 2017). "In this study, we demonstrate the expression of the miR-106b~25 cluster and its host gene MCM7 in a group of ACTH-producing PAs and characterize their utility to evaluate tumor invasiveness and clinical behavior." (PMID 28432562, 2017). "Applying these MCM family expression cutoff to Kaplan-Meier survival curve estimation revealed decreased survival probability for patients with tumor expressing high levels of MCM2, MCM3 and MCM7 (p < 0.05)." (PMID 25046975, 2014). "MCM7 is directly regulated by E2F and induced by HPV, and its mRNA was found differentially expressed between the two tumour groups." (PMID 18349847, 2008). "We found that increased doses of simvastatin (SVA), previously shown to inhibit MCM7, inhibited the growth of yBM cells similar to that of OS tumor cells and BMT, but did not affect control BM cells." (PMID 38182577, 2024). "The expression of the carcinoma-related genes Hgf, Myc, and Mcm7 was lower in KO livers than in FL livers, despite the absence of detectable tumor lesions in the liver upon histological examination at 12 weeks old." (PMID 39394459, 2024).
tumor (continued). "Notably, in Basal-SCCIS-tumor cells, DNA damage response-related replication genes (PCNA, MCM7) were significantly up-regulated." (PMID 38099574, 2023). "Among them, the top up-regulated genes in tumor cells were those related to cancer progression (eg, AREG, CCL3, PLEKHA5, VCAM1 and MCM7), which might be the targets of innovative treatments." (PMID 36417130, 2023). "Here we found fusion transcripts with MCM7 as 3′ partner in eight tumours, however none of them had WGS data available." (PMID 35182081, 2022). "Mcm7 is an E2F-responsive gene whose expression can be used as a readout for the ability of the MCPyV LT antigen to bind and inactivate the cellular tumor suppressor Rb through its LxCxE motif, which is retained in MCC tumor-derived truncated LT antigens." (PMID 33478104, 2021). "Moreover, some tumor suppressors and regulatory proteins such as the Rb tumor suppressor family and CDK inhibitors can bind to MCM7 and block MCM2-7 activity." (PMID 30937307, 2019). "The IHC index of MCM7 in HCC tumor tissues is much higher than nontumor tissues (P<0.05), suggesting that MCM7 is mainly overexpressed in HCC." (PMID 28182015, 2017). "In conclusion, the data indicate that compared with Mcm7 and Ki67, NEK2 may be a more effective tumor proliferation marker of poor prognosis for NSCLC patients, and that NEK2 may represent a novel potential target for NSCLC therapeutic intervention." (PMID 25202351, 2014). "We found a significant increase in MCM2 (3.5 fold), MCM3 (3.1 fold), MCM4 (4.3 fold), MCM5 (3.8 fold), MCM6 (3.5 fold), MCM7 (3.0 fold) and MCM10 (3.6 fold) expressions in tumor tissues (the average fold value of three grades) compared to the normal brain controls." (PMID 25046975, 2014). "Moreover, siRNA-mediated knockdown of MCM7 expression reduced GBM cell proliferation and also inhibited tumor growth in both xenograte and orthotopic mouse models of GBM." (PMID 25046975, 2014). "We reviewed each grade of tumor separately and investigated whether the expression of MCM2, MCM3 and MCM7 predicts patient survival within each subgroup." (PMID 25046975, 2014). "MCM7 expression does not show significant correlation with tumor stages (Spearman’s rho = −0.087, p = 0.557) or any difference in different types of lesion in comparison to normal (data not shown)." (PMID 23874974, 2013). "PCNA and MCM7 were ectopically expressed in the lower epithelial suprabasal layers of CIN1, and their expression expanded upwards in CIN3, reaching almost all tumor cells in CC samples." (PMID 22911850, 2012). "In addition to MCM7, the global mass spectrometry analysis of PB2 KD cells revealed many biological processes at 10- to 40-fold enrichment, such as positive regulation of the immune response to tumor cells and astrocyte activation." (PMID 40818975, 2025). "Importantly, it has been shown that HPV16 can likewise induce E2F responsive genes - especially MCM7 - in the absence of E7 in reproductive epithelia and tumours." (PMID 31640696, 2019). "Furthermore, our studies reveal proteins such as MCM7 as downstream mediators of the PLXNB2 interaction network that are required for PLXNB2-mediated tumor cluster formation but might not be sufficient to rescue surface protein-mediated intercellular crosstalk." (PMID 40818975, 2025). "Immunostaining of the DNA synthesis marker, minichromosome maintenance complex component 7 (MCM7), appeared to show increased intensity in the CTHRC1-knockdown tumors as compared to the control tumors, regardless of the tumor size." (PMID 26918341, 2016). "We then applied univariate analysis to evaluate associations between patient prognosis and several factors, including MCM7 expression, age, gender, histologic type (non-ADC versus ADC), pT stage (tumor size, T1 versus T2 + T3) and pN stage (node status, N0 versus N1+N2)." (PMID 21619671, 2011).
cancer (101 papers, 2008 to 2025). A tumor composed of atypical neoplastic, often pleomorphic cells that invade other tissues. "MCM7, a cell cycle-regulating protein, is frequently overexpressed in cancers and is associated with hyperproliferation and cancer progression." (PMID 40943553, 2025). "The involvement of MCM7 in cancer progression and its potential as a diagnostic marker have been proven for human cancers." (PMID 40943553, 2025). "According to one study, MK acts as an oncoprotein inhibitor for cancer therapy by inhibiting MCM7, which causes various types of cancers with extreme malignancy when levels are exceeded." (PMID 40483419, 2025). "It was reported that the variant allele of rs2070215 increases the expression of MCM7, therefore leading to cell proliferation, increasing the relapse rate and influencing cancer prognosis." (PMID 31936215, 2020). "Among these, p56Lyn-, Akt-, and integrin-linked kinase (ILK)-mediated MCM7 phosphorylation primarily correlates with the development of human cancer." (PMID 30062004, 2018). "Recent study show that decreasing MCM7 can inhibit the proliferation of Rb-deficient cancer cells." (PMID 32669967, 2020). "Similarly, elevated expression of the MCM7 gene, whose oncogenic potential has been widely discussed, was also associated with a higher risk of cancer recurrence." (PMID 29402894, 2018). "However, our findings of deceased MCM7 expression in ATP7B deficiency cells is consistent with previous observation of overexpression of MCM7 in cancers, which is the opposite extreme for apoptosis." (PMID 23843956, 2013). "Multiple human cancers are caused by the overexpression of the DNA replication licensing complex component MCM7.The present article describes the biogenic compounds screening against MCM7 protein using the in silico art of technique to find promising MCM7 inhibitors." (PMID 34641424, 2021). "Thus, Cy induced down regulation in Ras, LMO2, MCM4 and MCM7 genes might shed light on the mechanisms underlying the anti-cancer effects of Cy." (PMID 24466173, 2014). "Our marker set also encompasses the MCM7 gene, which is relevant to repairing double-strand DNA breaks and preventing genomic instability in cancers." (PMID 40279344, 2025). "Similar to MCM7, overexpression of miR-25-3p, miR-93-5p, and miR-106b-5p has been demonstrated in many human cancers, including ccRCC." (PMID 40943553, 2025). "Elevated expression of MCM7 enhances DNA synthesis, promotes cell proliferation, invasion, and contributes to overall cancer progression." (PMID 40943553, 2025). "Their localization within an intron of MCM7, a gene involved in DNA replication, suggests potential co-regulation and a link to cell proliferation and the cell cycle, central processes in both cancer and cardiac remodeling." (PMID 41155295, 2025). "Cancer patients with a higher expression of MCM5 and MCM7 were significantly linked with poor overall survival." (PMID 37384298, 2023). "miR-93, a member of the miR-106b-25 family, located within an intron of MCM7 gene, is highly expressed in a variety of cancers and acts as an oncogene." (PMID 36941991, 2023). "Aberrant expression of MCM7 has been reported in several types of cancers, and its expression leads to a poor prognosis in these patients." (PMID 37517032, 2023). "More and more details about MCM7’s function in the development of cancer are becoming available since it has been discovered to be amplified and overexpressed in a number of human malignancies." (PMID 37594635, 2023). "MCM4 mutation affected its interaction with MCM7 to induce the destabilization of MCM4/6/7 complex and contributed to cancer cell development." (PMID 37491836, 2023). "A total of 41 compounds were found as a potential inhibitor against MCM7 in human cancer and their compound identification number (CID) has been retrieved from the PubChem website in SDF file format (SM 1)." (PMID 35087187, 2022).
cancer (continued). "The relationship between cancer and MCM7 expression has been widely examined in the medical literature." (PMID 34144903, 2022). "In this study, we demonstrated that MCM7 mRNA expression was markedly down or up-regulated in human cancer." (PMID 35087187, 2022). "As the MCM7 overexpression plays a crucial role in cancer development, the study aimed to identify potential drug candidates against the protein to treat human cancer." (PMID 35087187, 2022). "Recently researcher has been found that MCM7 regulates the binding activity of MCM proteins that are highly associated with tumorigenesis and promotes cancer progression." (PMID 35087187, 2022). "MAGEC3 also upregulates a stress-related gene, WRNIP1, a DNA replication gene, MCM7, and cancer-related genes, XPO5 and ZSCAN16." (PMID 35158998, 2022). "MCM7 facilitates cancer procession through cyclin D1-dependent signaling and serves as a prognostic marker for patients with HCC." (PMID 35639708, 2022). "MCM7, the host gene of the miR-106b-93-25 cluster, and a transcription factor, is also upregulated in many cancers and its high expression is related to poor prognosis." (PMID 34572448, 2021). "The miR-106b-93-25 cluster, located in the intronic region of MCM7, is composed of highly conserved miR-106b, miR-93 and miR-25, which are upregulated in multiple cancer types." (PMID 34572448, 2021). "The MCM7 level was also increased in 52 cancer datasets and decreased in six cancer datasets compared to that in normal tissue datasets." (PMID 34178669, 2021). "Minichromosome maintenance complex component 7 (MCM7) is involved in replicative licensing and the synthesis of DNA, and its overexpression is a fascinating biomarker for various cancer types." (PMID 34641424, 2021). "This study paves the wave for further wet lab validation (in vitro and in vivo study) of these compounds in the form of novel inhibitor development against MCM7 to fight cancers." (PMID 34641424, 2021). "We observe that the mini-chromosome maintenance proteins (MCMs) MCM2, MCM3, MCM6 and MCM7, which were upregulated in most of the cancers, also regulate the expression of a significant number of high centrality genes in the network." (PMID 34728699, 2021). "Although miR-106b-93 cluster was reported to have an independent primary transcript unit from its host gene, our results showed that miR-106b/25 were significantly co-expressed with their host gene MCM7 across all the 21 cancers." (PMID 34572448, 2021). "It is suggested that hit compounds UEFS99, UEFS137, and UEFS428 pave the way for further bench work validation in novel inhibitor development against MCM7 to fight the cancers." (PMID 34641424, 2021). "For example, the miR-106b-93-25 cluster was co-transcribed with MCM7 across all cancer types (rmeta > 0.5, FDR < 0.01)." (PMID 34572448, 2021). "We demonstrate that cyclin E2 localises with core preRC (pre-replication complex) proteins (MCM2, MCM7) on the chromatin of cancer cells." (PMID 32823571, 2020). "We found an extensive nucleus staining of MCM7 in cancer tissues compared with a weak cytoplasmic staining in the paired nontumor tissues." (PMID 31186405, 2019). "Taken together, we identify ATO as a new potential inhibitor of MCM7 protein in cancer, which will shed light on the treatment of MCM7-overexpressed HCC." (PMID 31186405, 2019). "The correlation between Mcm and cancer was first proposed 20 years ago by an observation of increased levels of nuclear Mcm7-positive cells in the malignant form of cutaneous keratinocytic tumors." (PMID 29651420, 2018). "Of interest, many of the identified candidate proteins belong to protein families that already have cancer‐associated members (such as MCM6 and MCM7 proteins, MAPK8, or CDC7)." (PMID 29572294, 2018).
cancer (continued). "It is interesting to note that all six top-ranked genes proposed to be cancer-associated (PLK1, MCM2, MCM3, MCM7, MCM10 and SKP2) were downregulated by MP-HX in both cell lines." (PMID 30042885, 2018). "Up to this point, it is interesting to note that in both cell lines, MP-HX downregulated all six top-ranked genes (PLK1, MCM2, MCM3, MCM7, MCM10 and SKP2) that were proposed to be cancer-associated (Wu, Zhu & Zhang, 2012)." (PMID 30042885, 2018). "As MCM7 is essential for DNA replication, its abnormally high expression was detected in several different types of cancer." (PMID 28432562, 2017). "In Bi-L E7/K14-tTA/FancD2−/− mice, we likewise observed expression of MCM7 throughout the epithelial cells within the cancers and the cervical epithelium." (PMID 27190216, 2016). "MCM7 expression patterns confirm that cancers retained in Bi-L E7/K14-tTA/FancD2−/− mice treated with doxycycline are not dependent upon continued expression of HPV16 E7." (PMID 27190216, 2016). "MiR-93 is a miRNA from the miR-106b-25 cluster, located in intron 13 of the host gene MCM7 at chromosome 7q22, and plays a regulatory role in a variety of malignant tumours." (PMID 25578493, 2015). "MCM7 has also been shown to have a strong ability to promote cell cycle progression and with strong involvement in human cancers with overexpression inducing improper DNA synthesis." (PMID 26253138, 2015). "This miRNA cluster is upregulated in many human cancers, such as gastric, prostate, and pancreatic neuroendocrine tumors, The miRNAs of the miR-106b-93-25 cluster are co-transcribed in the context of the MCM7 primary transcript." (PMID 23028803, 2012). "Higher expression level of MCM7 is also observed in many cancers and regarded as an indicator of poor prognosis." (PMID 23028803, 2012). "Immunohistochemistry using an MCM7-specific antibody showed nuclear localization in cancer tissues, but nothing was detected in normal lung tissues." (PMID 21619671, 2011). "This work forms the basis for further functional studies, which will explore MCM7 as a potential therapeutic and prognostic target in lung and other cancers." (PMID 21619671, 2011). "Although knockdown of MCM7 expression by specific siRNAs notably suppressed the growth of cancer cells, significant growth suppression was hardly observed in the normal HFL-1 and CCD-18Co cells." (PMID 21619671, 2011). "In this study, we demonstrated that in various cancer tissues, expression levels of MCM7 were significantly high at both mRNA and protein levels whereas those in various normal tissues were generally low." (PMID 21619671, 2011). "Firstly, we examined the expression profile of MCM7 in various types of normal and cancer cell lines." (PMID 21619671, 2011). "In this study, we evaluated Minichromosome Maintenance Protein 7 (MCM7) as a novel therapeutic target in cancer." (PMID 21619671, 2011). "Since MCM7 expression was generally low in a number of normal tissues we examined, MCM7 has the characteristics of an ideal candidate for molecular targeted cancer therapy in various tumors and also as a good prognostic biomarker for NSCLC patients." (PMID 21619671, 2011). "Quantitative real-time PCR and western blot analyses showed that MCM7 expression levels in cancer cell lines were significantly higher than those in normal human cell lines at the RNA and protein levels." (PMID 21619671, 2011). "MCM7–miR-106b-25 complex consists of MCM7 “host gene” and three intronic microRNAs (miR-106b-5p, 93-5p, and 25-3p), localized on the 7q22 locus frequently amplified in human cancers, including ccRCC." (PMID 40943553, 2025). "The amplification of the MCM7–miR-106b-25 locus was reported in human cancers." (PMID 40943553, 2025). "MCM7 is expressed at low levels in normal tissue, but is frequently upregulated in human cancers." (PMID 40943553, 2025). "Interestingly, researchers discovered that Dasatinib inhibited the activity of the MCM7 protein, making it a promising cancer therapy." (PMID 37325063, 2023).